RNU6-1236P (RNA, U6 small nuclear 1236, pseudogene)
Gene: Small nuclear RNA gene on chromosome 3 (109,225,129 to 109,225,227, forward strand). Ensembl gene ENSG00000252889.
Homologues: Orthologues: chimpanzee U6 (100% identical), macaque U6 (94% identical), mouse Gm26187 (56% identical). Paralogues in human: RNU6-1209P (76% identical), RNU6-639P (76% identical), RNU6-254P (75% identical), RNU6-812P (75% identical), RNU6-1145P (74% identical), RNU6-1214P (74% identical), RNU6-189P (74% identical), RNU6-216P (74% identical), RNU6-38P (74% identical), RNU6-59P (74% identical), RNU6-797P (74% identical), RNU6-924P (74% identical), and 1284 more.